WNT7A (Wnt family member 7A)
Diseases named in the same sentence as WNT7A in open-access papers (continued):
Sharing a sentence is not in itself a finding about the gene and the disease.
tumor (continued). "In order to identify the mechanism/s through which Wnt7a has a tumor-suppressive role, we performed high-throughput RNA-seq on the lung tissues of wild-type and Wnt7a-null mice after urethane treatment (n=3)." (PMID 25728679, 2015). "The methylation status of ITGA9 and WNT7A promoters in NPC tumor biopsy samples was investigated by sequencing of clones after bisulfite conversion." (PMID 26372814, 2015). "In sum, these findings demonstrate that Wnt7a is a novel inducer of tumor-suppressive cellular senescence via the modulation of the expression of SKP2-mediated alternate senescence pathway." (PMID 25728679, 2015). "Taken together, these data suggest that Wnt7a has an important tumor-suppressive role in lung carcinogenesis." (PMID 25728679, 2015). "In the current study, we identify hsa-miR29b as a novel tumor suppressor, which is regulated by Wnt7a in NSCLC cells." (PMID 23862015, 2013). "The data from this study support the role of Wnt7a as a tumor suppressor in lung epithelial cells and emphasize the role of Wnt7a in maintaining an epithelial phenotype in adult lung tissue." (PMID 22403725, 2012). "We are interested in the role of non-canonical Wnt signaling in non-small lung cancer (NSCLC), specifically the tumor suppressive activities of Wnt7a and its receptor Frizzled 9 (Fzd9)." (PMID 22403725, 2012). "Secondly to verify that MSP determines methylation status of WNT7A 5′-CpG-island correctly, bisulfite sequencing was performed for 3 tumor samples that had revealed methylated WNT7A 5′-CpG island according to the MSP data." (PMID 23056560, 2012). "Methylation analysis revealed positive correlations between tumor stage, Fuhrman nuclear grade and WNT7A hypermethylation." (PMID 23056560, 2012). "The Wnt7a promoter has a higher percentage of methylation in NSCLC tumor tissue compared to matched normal lung tissue and methylation of the promoter region leads to decreased activity." (PMID 22403725, 2012). "We have also shown that the WNT7A gene possesses tumor suppression function by colony-formation and cell proliferation assays in RCC cell lines." (PMID 23056560, 2012). "The selection of A498 cells was informed by prior evidence demonstrating their responsiveness to 5-Aza-CdR-mediated demethylation and reactivation of tumor suppressor genes (e.g., WNT7A, KRT19, BTG3), confirming sufficient endogenous DNMT activity for pharmacological inhibition." (PMID 40866976, 2025). "Wnt7a expression also correlates with the degree of tumor differentiation in patients with OSCC." (PMID 40421179, 2025). "Notably, we observed a positive correlation between the WNT7A expression level and tumor differentiation (P < 0.05), and perineural invasion (P < 0.01)." (PMID 38246919, 2024). "Here, the expression of Wnt7a/Wnt7b was upregulated in tumor cells compared to a healthy colon." (PMID 36982422, 2023). "In mouse xenograft experiments, overexpression of WNT7A reduced the tumor volume." (PMID 36982422, 2023). "Through animal and cell experiments, we found that NE can affect the secretion of the chemokine CXCL9 and the immunosuppressive metabolite ADO in tumour cells by regulating the WNT7A/β-catenin signalling pathway, thereby inhibiting chemotaxis and function of CD8+ T cells." (PMID 36646807, 2023). "Although the evidence linking Wnt7a to tumor angiogenesis is rather limited, astrocyte-derived Wnt7a was shown to stimulate angiogenesis, suggesting that Wnt7a may play a role in tumor angiogenesis which also contributes to cancer cell metastasis." (PMID 36096830, 2022). "In contrast, in the lung FZD9 interacts with WNT7a to activate tumor suppressive signaling." (PMID 35924166, 2022). "Wnt7a protein is mainly expressed in tumor cells, and Wnt7b is mainly expressed in macrophages." (PMID 36209344, 2022). "Six overexpressed and mutated tumor antigens associated with poor prognosis and infiltration of antigen presenting cells were identified in PAAD, including ADAM9, EFNB2, MET, TMOD3, TPX2, and WNT7A." (PMID 33648511, 2021).
tumor (continued). "Here, in this paper, our results confirmed that WNT7A expression was markedly increased in poorly differentiated tumor tissues compared with matched well-differentiated tumor tissues and that EGF could cause an increase of WNT7A expression in OSCC cells." (PMID 32174831, 2020). "Finally, we examined the Wnt7a protein level on the tumor-derived cell lines (SMMC-7721, HepG2, Hep3B, and Huh-7) by Western blot analysis." (PMID 31886205, 2019). "A new finding in this study is that WNT7A overexpression can promote tumor cell apoptosis." (PMID 31886205, 2019). "However, the specific mechanisms of Wnt7a regulation of tumor-suppressive signaling in HCC required further investigation." (PMID 31886205, 2019). "Using transwell assay, we revealed that WNT7A overexpression inhibited tumor cell migration." (PMID 31886205, 2019). "The proteins of Wnt4, Wnt 5a, Wnt7a, and Wnt14 have been studied in the OS cell lines, implying that Wnt pathway may serve as a tumor activator." (PMID 28665975, 2017). "Interestingly, we found that tumor cell proliferation-related genes of Wnt7a, SUFU, PTCH2, and Gli2 changed significantly." (PMID 28640224, 2017). "Moreover, we evaluated the expression levels of SUFU and Wnt7a in tumor tissues in the mice by using RT-qPCR." (PMID 28640224, 2017). "Indeed, FACSorted CAFs from Wnt7a high 410.4/4T1 tumours consistently show higher levels of Tgfb1 expression as compared with Wnt7a low 4T07 tumours." (PMID 26777421, 2016). "Our past miRNA studies of BC cells showed that clustered miRNAs (including miR-1/133a (targeting TAGLN2), miR-23b/27b/24-1 (targeting EGFR, MET, and FOXM1), and miR-195/497 (targeting BIRC5 and WNT7A)) act as tumor-suppressive miRNAs through their regulation of several oncogenic genes and pathways." (PMID 27072587, 2016). "While our data show that aggressive tumour cells secrete Wnt7a, we next sought to determine whether there are other sources of Wnt7a within the tumour." (PMID 26777421, 2016). "We evaluated Wnt7A expression in 50 surgically resected tumor specimens using quantitative PCR." (PMID 25632963, 2015). "Interestingly, knockdown of hsa-miR29b was enough to abrogate the tumor suppressive effects of Wnt7a/Frizzled9 signaling in NSCLC cells, suggesting that hsa-miR29b is an important mediator of β-catenin independent signaling." (PMID 23862015, 2013). "Importantly, we have found that decreased WNT7A expression positively correlates with tumor progression." (PMID 23056560, 2012). "However, another study was in contrast to the opinion above concerning the tumor suppressing function of Wnt7a." (PMID 23304155, 2012). "Wnt7a is known to be a tumor suppressor that is lost in NSCLC, but no mechanism of loss has been established." (PMID 22403725, 2012). "However, the biological role of WNT7A action in cancer is controversial at present; some evidence supports its activity as an oncogene, but there is also evidence of its tumor suppressor action." (PMID 22313908, 2012). "In fact, Wnt7a has recently been described to have a tumor suppressing effect in other studies." (PMID 23304155, 2012). "Interestingly, Wnt Family Member 7A (WNT7A) was only secreted by tumour cells themselves." (PMID 37370765, 2023). "Therefore, we speculated that NE regulates the secretion of CXCL9 and ADO in tumour cells through the WNT7A/β-catenin signalling pathway." (PMID 36646807, 2023). "Importantly, this study shows that NE can affect the secretion of the chemokine CXCL9 and the immunosuppressive metabolite ADO in tumour cells by regulating the WNT7A/β-catenin signalling pathway, thereby reducing the chemotaxis and function of CD8+ T cells, resulting in anti-PD-1 mAb resistance." (PMID 36646807, 2023). "Thus, WNT7a is also able to exert tumor-suppressive effects." (PMID 35885035, 2022). "Previous research indicated that Wnt7a could inhibit tumor by regulating SKP2/P21 signaling." (PMID 31886205, 2019).
tumor (continued). "Regarding pathway assignments of at least 20 HRO tumours, 10 top-ranked genes, of which 9 were lost in 3p, were linked with 7 to 45 pathways (n = 280) comprising RAF1 (45 PWs), RHOA (25 PWs), IPTR1 (22 PWs), CACNA1D, ITGA9 (8PWs), WNT7A (8 PWs) TLR9 (7PWS9, LAMB2 (7 PWs) and ARPC4 (6 PWs)." (PMID 28486536, 2017). "Importantly, in a complementary approach where Wnt7a-treated fibroblasts are allowed to remodel the 3D matrix but are killed before tumour cell invasion is assessed, we demonstrate that the increased tumour cell invasion is dependent on the ability of the treated fibroblasts to remodel the matrix." (PMID 26777421, 2016). "Finally, our results suggest that Wnt7A is possibly a novel tumor-suppressor gene in MPM." (PMID 25632963, 2015). "Thus, the WNT7A gene does indeed possess tumor suppressor properties in RCCs." (PMID 23056560, 2012). "The functions of Wnt7a may therefore be dependent on the organ and tumor type examined." (PMID 23304155, 2012). "VEGF, TGF-β, CXCR4, Cav-1, Wnt7a, EGFR and EPHA2 enhance vascular formation and influence tumor microenvironment dynamics." (PMID 40486870, 2025). "The eight genes (CAMK2N1, WNT7A, F2RL1, AREG, DEFB1, CNFN, TGFBI, and CAV1) included in the signature have been extensively studied and are known to be involved in tumor progression and EMT process." (PMID 37907576, 2023). "To demonstrate the role of WNT7A in the regulation of CXCL9 and ADO secretion by NE in tumour cells, we transfected tumour cells with WNT7A-shRNA lentivirus or scramble-shRNA lentivirus (NC)." (PMID 36646807, 2023). "Conversely, WNT5A, WNT7B, WNT2, WNT7A, WNT10A and WNT3 were tumor-positive WNTs, which significantly increased in many carcinomas." (PMID 35850748, 2022). "WNT7a binds to FZD9 and signals to peroxisome proliferator activated receptor gamma (PPARγ) through an Erk5-dependent cascade, leading to anti-tumor signaling, including increasing epithelial and reducing mesenchymal gene expression." (PMID 35924166, 2022). "In contrast, we observed a negative correlation of DSCAM-AS1 with the highly upregulated WNT7A gene (rho = −0.25, p = 5.3 × 10−5) (HEC-1B), which is reported to act as tumor suppressor in endometrium." (PMID 35885035, 2022). "Further analysis of the correlation between the WNT gene family and clinicopathological parameters of UCEC showed that the WNT1, WNT3, WNT7A, WNT7B, WNT8B, and WNT10A genes were expressed at significantly different levels at different tumor stages." (PMID 34565373, 2021). "Nevertheless, care should be taken when interpreting these findings because TGF‐β can increase CSF2 in uterine epithelial cells, WNT7A in chondrocytes, KRT17 in tumor epithelial cells, and SERPINE1 in renal epithelial cells." (PMID 34789212, 2021). "Consistent with previous reports in PDAC organoids, WNT5A, WNT7A, WNT7B, and WNT10A mRNA were highly expressed in PDCLs, suggesting a tumor cell-intrinsic origin for these WNT ligands." (PMID 32402285, 2020). "In this study, we first evaluated the relationship between Wnt7a mRNA expression levels and overall survival of patients and worked out the Wnt7a expression profile changes in HCC tissues and tumor-derived cell lines." (PMID 31886205, 2019). "To verify the result, we also performed qRT-PCR to evaluate the WNT7A expression in 20 pairs of PDAC and adjacent-non tumor tissue from Ren Ji cohort." (PMID 30361522, 2018). "We detected the gene expression with significant differences of SUFU and Wnt7a in RL95-2 cells, KLE cells, and RL95-2 xenografts tumor tissues by RT-qPCR and Western blotting." (PMID 28640224, 2017). "In summary, the WNT7A gene is inactivated by genetic/epigenetic alterations in clear cell RCC and demonstrates tumor suppressor properties." (PMID 23056560, 2012).
tumor (continued). "In conclusion, this study uncovers a novel reciprocal activation loop between tumor cells and CAFs in BLCA lung metastases, where tumor-secreted WNT7A activates resident pulmonary CAFs, which in turn enhance tumor malignancy through exosomal delivery of miR-1910-5p." (PMID 42236896, 2026). "Furthermore, in a patient-derived xenograft (PDX) tumor model, high expression of WNT7A and phosphorylated STAT3 was observed, which positively correlated with tumor progression." (PMID 38246919, 2024). "Furthermore, the mRNA expression levels of FAM83A, LY6D, MET, MUC16, MYEOV, and WNT7A were elevated in PAAD tissues, while the protein expression patterns of LY6D, MET, MUC16, and WNT7A were higher in tumor sample." (PMID 38169540, 2024). "WNT7A, a member of the WNT ligand family, plays diverse roles in different tumor types." (PMID 38246919, 2024). "Particularly intriguing were the levels and expression patterns of Wnt7a/b, which is clearly expressed by the tumor epithelium and organoids, but not in the healthy epithelium." (PMID 34849464, 2021). "Furthermore, miR-361 also suppressed the expression of multiple prometastatic genes and tumor microenvironment-related genes, including MEF2D, ROCK1, WNT7A, VEGF-A, PDE4B, and KPNA4." (PMID 31287002, 2019). "Interestingly, the genes of SUFU, Gli2, Wnt7a, and PTCH2 closely related to tumor cell proliferation were significantly upregulated." (PMID 28640224, 2017). "TLX, which is also induced by SOX2 in neurogenic areas, represses the expression of the tumor suppressing gene phosphatase and tensin homologue (PTEN) and various micro RNAs involved in cell differentiation, while promoting the expression of Wnt7a and other factors involved in NPC proliferation." (PMID 28493916, 2017). "By gene expression profiling of aggressive and non-aggressive tumours, we identify Wnt7a as a key tumour cell-secreted factor that promotes fibroblast recruitment and activation in three-dimensional (3D) in vitro assays and in vivo." (PMID 26777421, 2016). "Wnt7A expression differed significantly between the 11 paired normal and tumor tissues (P=0.005), and by tumor stage, gender, smoking status and ethnicity." (PMID 25632963, 2015). "Interestingly, knockdown of hsa-miR29b was enough to abrogate the tumor suppressive effects of Wnt7a and Fzd9 expression in NSCLC cells, suggesting that Wnt7a and/or hsa-miR29b plays a critical during lung tumorigenesis." (PMID 23862015, 2013). "Wnt7a is involved in noncanonical Wnt signaling and also inhibits tumor growth." (PMID 37901797, 2023). "In addition, lncRNA-NEAT1 directly targets the expression of many prometastatic genes and tumor microenvironment-related genes (such as STAT3, WNT7A and VEGF-A) by interacting with miR-361, while miR-361 can inhibit tumor proliferation, invasion, stemness and paclitaxel resistance." (PMID 36601121, 2022). "Then, we found that the expression of WNT7A acted as an independent prognostic factor for PDAC patients, patients with high expression of WNT7A have a dramatically shorter survival time than those with low expression of WNT7A independent of tumor differentiation and lymph node metastasis." (PMID 30361522, 2018). "Using this model we identified Wnt7a as a novel factor secreted by aggressive tumour cells that drives the acquisition of a desmoplastic response characterized by an activated CAF phenotype, which is capable of matrix remodelling and promotion of tumour cell invasion." (PMID 26777421, 2016). "Conversely, they also found, Wnt-7a, another noncanonical ligand that played a tumor suppressor role in NSCLC, which could suppress NSCLC development and was often downregulated in this type of cancer." (PMID 27895670, 2016). "qPCR analysis of different cell populations freshly isolated from the tumours demonstrates that indeed aggressive tumour cells are the principal sources of Wnt7a, with little or no expression detected in CAFs, immune cell populations or less aggressive 4T07 tumour cells." (PMID 26777421, 2016).
tumor (continued). "Therefore, by using several distinct approaches, we showed that the tumor-suppressive effects of Wnt7a are independent of β-catenin." (PMID 25728679, 2015). "The ITGA9 promoter showed marked differentially methylation between tumor and control tissue, whereas no differentially methylation could be detected for the WNT7A promoter." (PMID 26372814, 2015). "However, a large number of SA-β-gal-positive cells, predominantly in the tumor area, were observed in lung sections of the wild-type mice after urethane treatment, whereas Wnt7a-null mice, on the contrary, showed reduced or no SA-β-gal staining." (PMID 25728679, 2015). "Wnt7a appears to be unique in the literature to date, as no other Wnt has been identified in NSCLC as a tumor suppressor or as relevant to the maintenance of a lung epithelial phenotype." (PMID 22403725, 2012). "Strong expression of ITGA9 and WNT7A was observed in membrane and cytoplasm of adjacent control nasopharyngeal epithelium cells, while weak or no expression of ITGA9 and WNT7A was observed in NPC tumor cells." (PMID 26372814, 2015). "Furthermore, we evaluated the expression of WNT7A at protein level using PDAC tissue microarrays (TMA) which containing a cohort of 80 paired PDAC and normal pancreas tissue and another 20 non-paired tumor tissue." (PMID 30361522, 2018).